GTF2A1 (general transcription factor IIA subunit 1)
Description:
TFIIA is a component of the transcription machinery of RNA polymerase II and plays an important role in transcriptional activation. TFIIA in a complex with TBP mediates transcriptional activity.
Synonyms: TFIIA-42; TF2A1; TFIIA; TFIIAL
Tractability: Small molecule: a structure with a bound ligand is known; a high-quality ligand is known. PROTAC: ubiquitination databases record sites on it; a small molecule that binds it is known.
Target class: Transcription factor
Gene: Protein-coding gene on chromosome 14 (81,175,452 to 81,221,377, reverse strand). Ensembl gene ENSG00000165417.
Subcellular location: Nucleus
Subcellular location (Human Protein Atlas): Nucleoplasm; Cytosol
Pathways (Reactome):
Gene expression (Transcription): RNA Polymerase II Pre-transcription Events; RNA Polymerase II Promoter Escape; RNA Polymerase II Transcription Initiation; RNA Polymerase II Transcription Initiation And Promoter Clearance; RNA Polymerase II Transcription Pre-Initiation And Promoter Opening; RNA polymerase II transcribes snRNA genes
Disease: HIV Transcription Initiation; RNA Polymerase II HIV Promoter Escape; Transcription of the HIV genome
Signal Transduction: Estrogen-dependent gene expression
Gene Ontology:
Molecular function: DNA binding; protein binding; protein heterodimerization activity; RNA polymerase II core promoter sequence-specific DNA binding; RNA polymerase II general transcription initiation factor activity; RNA polymerase II general transcription initiation factor binding; TBP-class protein binding; RNA polymerase II-specific DNA-binding transcription factor binding
Biological process: positive regulation of transcription by RNA polymerase II; positive regulation of transcription initiation by RNA polymerase II; transcription by RNA polymerase II; RNA polymerase II preinitiation complex assembly; transcription initiation at RNA polymerase II promoter
Cellular component: nucleoplasm; nucleus; transcription factor TFIIA complex; transcription factor TFIID complex; transcription preinitiation complex; cytoplasm
Genetic constraint (gnomAD): Loss-of-function variants: 7 observed, 30.94 expected, observed/expected ratio (o/e) 0.23, 90% interval 0.13 to 0.43. The upper end of that interval is the gene's LOEUF score, 0.43, which puts it in group 1 of 6, group 1 being the genes least tolerant of losing a copy. Missense variants: 205 observed, 257.8 expected, observed/expected ratio (o/e) 0.8, 90% interval 0.71 to 0.89. Synonymous variants: 80 observed, 92.14 expected, observed/expected ratio (o/e) 0.87, 90% interval 0.72 to 1.05.
Homologues: Orthologues: macaque GTF2A1 (100% identical), pig GTF2A1 (99% identical), dog GTF2A1 (99% identical), rat Gtf2a1 (99% identical), chimpanzee GTF2A1 (97% identical), mouse Gtf2a1 (97% identical), guinea pig GTF2A1 (96% identical), tropical clawed frog gtf2a1 (76% identical), zebrafish gtf2a1 (70% identical), Drosophila melanogaster TfIIA-L (32% identical), Caenorhabditis elegans pqn-51 (29% identical). Paralogues in human: GTF2A1L (36% identical).
Diseases named in the same sentence as GTF2A1 in open-access papers:
GTF2A1 is named in the same sentence as 4 diseases in open-access papers, as found by Europe PMC text mining. Sharing a sentence is not in itself a finding about the gene and the disease. The quoted sentences say what the papers report.
autism (1 paper, 2024). Persistent deficits in social interaction and communication and interaction as well as a markedly restricted repertoire of activity and interest as well as repetitive patterns of behavior. "Four Qualifying variants in B1 genes (with published indirect association with autism) were identified in four subjects, in the following genes: BRPF3, GTF2A1, POGLUT3, and TMEM184B, including a de novo loss-of-function variant in POGLUT3." (PMID 38256266, 2024).
ovarian tumor (1 paper, 2018). "For the remaining three regions, the 50 kb selected region on chromosome 5 includes two genes; the TSHR locus involved in metabolic regulation and reproduction process and GTF2A1, a candidate biomarker for detecting ovarian tumor." (PMID 30079080, 2018).
GTF2A1 also shares sentences with these, for which no sentence is quoted: cancer (1 paper); neurological diseases (1).